IL33 (interleukin 33)
Diseases named in the same sentence as IL33 in open-access papers (continued):
Sharing a sentence is not in itself a finding about the gene and the disease.
asthma (continued). "Studies have shown that IL-33 and TSLP modulate migration of CD34+ progenitor cells in patients with asthma, further enhancing eosinophilia and basophilia, and also inversely correlate with lung function." (PMID 36311787, 2022). "In regards to upstream mediators of asthma-like inflammation, HMPV has been shown to induce in vitro expression of IL-33 and TSLP in human alveolar epithelial cells." (PMID 35493465, 2022). "Consistently, we detected IL-4, IL-5, IL-13, IL-25, IL-10, IL-33, and TSLP in induced sputum of asthma and proved a positive correlation between BIRC3 and these cytokines." (PMID 35287655, 2022). "IL-33 and TNF levels were significantly higher in patients with CPA than in those with asthma (p < 0.05)." (PMID 35628692, 2022). "Therefore, NETs could contribute to asthma pathobiology and exacerbations through the loss of integrity of the bronchial epithelium and the release of “upstream cytokines’’ such as alarmins (e.g., TSLP, IL-33)." (PMID 36359917, 2022). "Meanwhile, multiple studies suggest that ciliated cells are a source of cytokines, such as IL33 and TSLP, in asthma." (PMID 35627266, 2022). "In models of asthma and parasitic infections, blocking any of IL-25, IL-33, or TSLP alone showed only modest results, while combinatorial targeting of IL-33, IL-25 and TSLP significantly reduced collagen expression and fibrosis." (PMID 38566909, 2022). "One cell type that also produces IL‐5 and IL‐13 in response to IL‐33 is the mast cell, and as TGF‐β has been shown to suppress IL‐33–induced mast cell function in the context of asthma, this population is a prime candidate for further investigation." (PMID 35758054, 2022). "The potential importance of the IL-33/ST2 axis in asthma is supported by several studies in which IL-33, ST2 and secretory ST2 (sST2) are increased in asthma compared to healthy controls and positively correlate with disease severity." (PMID 36366528, 2022). "Other therapeutic targets for both AD and asthma are the alarmins TSLP and IL-33, released from barrier tissues which activate the innate immune response." (PMID 35743678, 2022). "In a mouse model of asthma induced by prolonged HDM, targeting IL-33 using a neutralizing antibody normalised established eosinophilic, neutrophilic, and ST2+CD4+ T-cell infiltration and improved remodeling of both the lung epithelium and parenchyma." (PMID 36311787, 2022). "Other studies are under way now to investigate the efficacy of targeting the IL-33 pathway in asthma including melrilimab, which inhibits ST2, and tozorakimab, a phase II study with anti-IL-33 which has been completed and the data are currently under analysis." (PMID 36311787, 2022). "This makes it a first-in-class candidate for a new group of antibodies targeting alarmins – key epithelial inflammatory cytokines involved in asthma pathogenesis (TSLP, IL-25 and IL-33)." (PMID 36561741, 2022). "Airway epithelial cells produce IL-33, IL-25, and thymic stromal lymphopoietin (TSLP) under allergen stimulation in the type 2 immune reaction of asthma." (PMID 36578010, 2022). "Epithelial cell-derived mediators including the alarmin cytokines IL-25, IL-33, and thymic stromal lymphopoietin (TSLP) have emerged as key players in propagating asthma pathogenesis." (PMID 35406669, 2022). "ILC2 from asthma patients have shown higher level of IRF7 than those from healthy donors and IRF7 expression was also reported in murine lung ILC2 upon papain or IL-33 stimulation." (PMID 36506643, 2022). "It is commonly thought that epithelial-derived alarmins (IL-33, TSLP, IL-25) play an upstream role in the pathogenesis of asthma where basophil-derived cytokines are a pivotal component of allergic inflammation." (PMID 35693823, 2022). "On the other hand, several pro-inflammatory factors are involved in pathological processes of the diseased airway epithelium: IL33, TSLP and TGF-β1 are known regulators in common airway diseases like asthma, allergic rhinitis, COPD or cystic fibrosis." (PMID 35782511, 2022).
asthma (continued). "Epithelial-derived alarmins (IL-33, TSLP, and IL-25) play an upstream role in the pathogenesis of asthma." (PMID 35693823, 2022). "We also studied epithelial-cell-derived IL-33, IL-25, and TSLP, which were regarded as alarmins and played pivotal roles in the initiation of allergic inflammation in asthma." (PMID 35983066, 2022). "This highlights the potential for a gene-environment interaction involving IL33 and HRV in MCs to contribute to virus-induced asthma exacerbations." (PMID 36366528, 2022). "The epithelial cell–derived cytokines IL-25, IL-33, and thymic stromal lymphopoietin (TSLP) initiate type 2 inflammation in allergic diseases, including asthma." (PMID 33945508, 2021). "Our data on airway IL-25, IL-33, and TSLP expression in asthma patients provide evidence for the potentially novel therapies targeting these cytokines in China." (PMID 33945508, 2021). "IL-33 effects would be auto-amplified by IL-33 induction of IL-33 release and ST2 expression and sST2 release, as observed recently for asthma." (PMID 34441830, 2021). "In order to write this narrative review, a literature search was carried out using the PubMed database, and as search words, we chose ‘asthma’, ‘alarmins’, ‘TSLP’, ‘IL-33′, ‘IL-25′, ‘anti-alarmins’, and ‘tezepelumab’." (PMID 34572294, 2021). "Similar to IL-33, TSLP and IL-25 can also be detected in increased amounts in the tissues of patients with asthma or atopic dermatitis, and genome-wide analyses demonstrate an association of these cytokines with allergic diseases." (PMID 33615121, 2021). "The airway epithelium is usually the first line of defense that is exposed to inhaled allergens and pathogens, releasing alarmins (including IL-25, IL-33, and TSLP) to propagate the development and exacerbation of asthma." (PMID 35126350, 2021). "miR-155 knockout HDM sensitized mice displaced low levels of IL-33 and ILC2, suggesting that HDM induces asthma through the critical role of miR-155." (PMID 34566492, 2021). "IL-33 levels in asthmatics compared to controls have been significantly higher within the peripheral blood, and IL-33 levels were negatively correlated to FEV1 and positively correlated to asthma severity." (PMID 33917396, 2021). "In parallel, an antibody targeting IL‐33, REGN3500, is currently being tested in AD and asthma as monotherapy or in combination with dupilumab (NCT03736967, NCT03112577, NCT03736967)." (PMID 34617355, 2021). "To further investigate the effect of IL-33 on the PM exposure-aggravated airway inflammation, we administered an IL-33 neutralizing antibody before PM exposure in HDM-induced asthma models." (PMID 34254951, 2021). "To date, there have been few head-to-head studies of IL-25, IL-33, and TSLP expression in human asthma." (PMID 33945508, 2021). "Airway miR-206 antagonism before HDM challenge suppressed IL-25, IL-33, and Tslp expression; ILC2 expansion; type 2 cytokine expression; and the cardinal features of asthma in mice." (PMID 33945508, 2021). "Nevertheless, anti-IL-33 and ST2 treatment reduced airway inflammation in a murine model of asthma and found that both treatments reduced the total cell counts and eosinophil counts in BAL fluid and significantly reduced the Th2 cytokine." (PMID 33919759, 2021). "Our results suggested that IL-33, ST2, and NF-κB can serve as therapeutic targets in the treatment of RSV infected asthma." (PMID 34395633, 2021). "We explored the influence of CD200R dependent stimulation of human ILC2s in context of asthma, and demonstrated that expression of CD200R is inducible on human ILC2s by IL-33 in a time-dependent manner." (PMID 33953190, 2021). "IL-33 promotes the ILC2 response, which secretes a large amount of IL-5 and IL-13 in allergic inflammation in asthma patients." (PMID 33722239, 2021). "Airway epithelial cytokines IL-25, IL-33, and TSLP play important roles in the innate immune response to allergens and promote Th2 immune responses in asthma." (PMID 35126350, 2021).
asthma (continued). "Some genes such as TSLP, IL-33 and its receptor IL1RL1 have well-established asthma inflammatory roles." (PMID 35386986, 2021). "Thus, IL-33 plays a major role in the initiation and development of type 2 immune responses, which are essential during host infection by helminths for example, but which, on the other hand, contribute to the development of various allergic diseases, such as asthma or atopic dermatitis." (PMID 35011670, 2021). "IL-33 expression has been also identified in human airway smooth muscle (ASM) and HLMCs in mild-to-moderate asthma." (PMID 33445787, 2021). "An anti-IL-33 monocloclonal antibody, REGN3500, has been shown to prevent airway remodeling in a murine model of house dust-mite-induced asthma and to reduce eosinophyls infiltration and airway hyperreactivity in an ovalbumin induced asthma murine model." (PMID 34680614, 2021). "Finally, the expression level of IL-6, IL-8, and IL-33 have been detected using the ELISA kits, and Pearson's correlation analysis was performed to investigate the relationship between the level of miR-3934 in PBMCs and the serum expression of those inflammatory cytokines in asthma patients." (PMID 33506046, 2021). "All these data support the critical role of IL-25, IL-33, and TSLP in asthma pathogenesis and type 2-driven inflammation." (PMID 34608100, 2021). "Co-exposure to HDM and benzo(a)pyrene has also been shown to enhance IL-33 and TSLP production in an asthma mouse model." (PMID 34977086, 2021). "Furthermore, mouse models of asthma have revealed that the genetic depletion of IL-33 results in a marked reduction of eosinophilic inflammation and mucus secretion following aerosol allergen exposure, indicating the key role of IL-33 in the pathogenesis of asthma." (PMID 33597946, 2020). "The IL-33/ST2 axis is indeed a potential drug target for individuals with uncontrolled eosinophilic conditions, including asthma." (PMID 32466530, 2020). "In the present study, we demonstrated that IL-33 increased the expression of CD146, which promoted the EMT process in asthma." (PMID 32793232, 2020). "Our findings in the humanized mouse model demonstrate that PD-1 agonist elicits an efficient suppression of activated ILC2s and suppresses AHR as well as lung inflammation in IL-33 and HDM-induced asthma." (PMID 32778730, 2020). "An interesting observation is the correlation between IL-33 and CHI3L1 (YKL-40) mRNA expression in asthma and COPD suggesting possible common pathways of these two mediators." (PMID 32842623, 2020). "In a chronic asthma model in IL-33-deficient mice, CD146 expression was decreased in the pulmonary tissues, accompanied by increased E-cadherin expression, suggesting that IL-33 is essential in the CD146 expression and airway remodeling observed in asthma." (PMID 32793232, 2020). "Current knowledge suggests that airway epithelial damage triggered by viral infections promotes the production of IL-25, IL-33, and thymic stromal lymphopoietin (TSLP), which in turn leads to the activation of ILC2 and exacerbation of asthma." (PMID 32823491, 2020). "This previous study identified genes on chromosomes 2 (IL1RL1/IL18R1), 6 (HLA-DQ), 9 (IL33), 15 (SMAD3), 17 (ORMDL3/GSDMB), and 22 (IL2RB) correlated with asthma." (PMID 32512817, 2020). "To demonstrate the significance of IL-33/ST2 in CD146 expression, we developed an asthma model in wild-type mice and IL-33 KO mice." (PMID 32793232, 2020). "The regulation of IL-33 signaling related to CD146 expression and the EMT process in asthma, however, remains largely elusive." (PMID 32793232, 2020). "The IL-33/ST2 pathway plays an important role in the development and maintenance of allergic inflammatory responses and asthma." (PMID 32486265, 2020). "Collectively, these studies demonstrate for the first time that agonistic activation of PD-1 suppresses AHR in IL-33- and HDM-induced asthma models, and crucially suggest a new specific therapy for asthmatic allergies." (PMID 32778730, 2020).
asthma (continued). "In support of this, IL-33 has been shown to be upregulated in the airway epithelium and BAL fluid from individuals with moderate to severe asthma, and release of IL-33 is increased during experimental RV-induced asthma exacerbation." (PMID 33255348, 2020). "In a clinically-relevant mouse model of asthma, intra-tracheal cockroach antigen treatment induced Glrx protein in wild type mouse lungs but Glrx induction was attenuated in IL-33 knockout mouse lungs, suggesting that IL-33 may regulate Glrx induction in vivo in response to allergen challenge." (PMID 30682073, 2019). "Bronchial epithelial cell injury leads to production of type 2 alarmins such as IL-33 and TSLP, also in asthma." (PMID 30778348, 2019). "DNA methylation in promoter regions of IL33 and IL1R1 in asthma from bronchial epithelial cells is decreased." (PMID 31731604, 2019). "The IL-33/ST2 axis plays an important role in several acute and chronic inflammatory diseases, including asthma and rheumatoid arthritis." (PMID 30769901, 2019). "Mast cells are normally located just beneath epithelial cells, and in asthma, they are also found within the intraepithelial cell layer, and they are therefore capable of rapidly responding to TSLP and IL-33 released from epithelial cells." (PMID 31275312, 2019). "In particular, the activation of the IL-33/ST2-involving Th2/IL-31 immune response has a crucial role for the development of allergic inflammation, such as in asthma." (PMID 31766607, 2019). "Chronic pulmonary obstructive disease (COPD), is a progressive inflammatory condition, in which an increased expression of IL-33 and the ST2 receptor, similarly to asthma, has been observed." (PMID 31057533, 2019). "In this domain, IL-33 induces IL-5 and IL-13 release by ILC2, playing a key-role in the framework of allergic inflammation, including asthma and atopic dermatitis." (PMID 30769901, 2019). "Release of epithelial cytokines, IL-33, IL-25, and TSLP, is the initial process during asthma exacerbation." (PMID 29977243, 2018). "The involvement of IL-33/ST2 pathway has been incriminated in numerous diseases and conditions, such as in asthma and myocardial infarction." (PMID 29507527, 2018). "Treatment with anti-IL-25 or anti-IL-33 neutralizing antibody, or TSLP receptor (TSLPR) KO attenuates asthma-like phenotype and ILC2 expansion in HRV infected immature mice." (PMID 30513770, 2018). "In particular, IL-33 activates ILC-2, which promote persistence of airway eosinophilia in patients with severe asthma refractory to steroids via production of IL-5 and IL-13." (PMID 30386455, 2018). "Positive feedback between IGF-1 and Th2 cytokines has been documented in asthma, as IGF-1 is inducible by repetitive intranasal challenge with IL-25 or IL-33 in murine asthma models." (PMID 30018981, 2018). "Enhanced secretion of IL-33 by respiratory epithelium could promote the smooth muscle contraction of the airway, airway hyper-responsiveness, and the aggravation of inflammatory response during allergic sensitization in childhood and presumably might affect subsequent asthma development." (PMID 30544846, 2018). "It appears that the IL-33/ST2 axis has a crucial role in some chronic immune inflammatory disorders, such as asthma, rheumatoid arthritis, and anaphylactic shock." (PMID 28614418, 2017). "Type-2 innate lymphoid cells (ILC2s) respond to the cytokines of thymic stromal lymphopoietin (TSLP), interleukin (IL)-25 and IL-33, thus contributing to airway diseases such as CRS and asthma." (PMID 28199345, 2017). "On the other hand, various genetic studies in humans have identified both IL-33 and its receptor ST2, as being key regulators in the development of asthma and to have a strong Th2- promoting ability in animal models of asthma." (PMID 29206851, 2017). "The IL‐33/ST2 pathway plays an important role in inflammatory and immunity diseases, including asthma, atopic dermatitis and coronary artery disease." (PMID 28121058, 2017).
asthma (continued). "Roles of the cytokines IL-33, thymic stromal lymphopoietin (TSLP) and IL-25 in asthma are receiving considerable interest." (PMID 26879906, 2016). "In this study we demonstrated that HDM-induced experimental asthma involved induction of lung tissue gene expression of four inflammatory cytokines as well as two upstream TH2- cytokines, IL-33 and TSLP." (PMID 26879906, 2016). "Three bronchial epithelial upstream cytokines; IL-33, TSLP and IL-25 are considered to trigger type-2 inflammation in asthma." (PMID 26879906, 2016). "Both IL‐33 and CXCL8/IL‐8 are promising new targets for prevention and therapy of wheezing and asthma." (PMID 26734461, 2015). "IL-25, IL-33 and/or TSLP were increased in specimens from patients with asthma and in inflamed skin lesions of patients with atopic dermatitis." (PMID 26230091, 2015). "IL-33 increased AHR in vivo and in lung slices and plays a key role in rhinovirus-induced asthma exacerbations." (PMID 25683166, 2015). "Therefore, IL-33 may present an important target to modulate mast cell–ASM crosstalk in asthma." (PMID 25683166, 2015). "IL-33 and TNF-α expression in lung tissues from asthmatic subjects increases with the severity of asthma." (PMID 24822215, 2014). "The IL-33/IL1RL1 pathway plays an important role in host defense and in autoimmune, allergic, and chronic inflammatory disorders, such as asthma, dermatitis, rhinitis, arthritis, diabetes mellitus, atherosclerosis, and Alzheimer’s disease." (PMID 23634226, 2013). "Subsequent studies have shown increased levels of IL-25, IL-33, and TSLP in patients with asthma that all have the potential to active ILC2." (PMID 24876829, 2013). "It is of interest that previously a positive correlation between IL-33 and TNF-α expression in the lung tissues in patients with asthma has been described suggesting a role of IL-33 in the pathogenesis of that disease." (PMID 23567618, 2013). "The IL-33/ST2 axis appears to play an important role in several chronic inflammatory disorders, including asthma, rheumatoid, arthritis, and anaphylactic shock." (PMID 23585867, 2013). "ILC2 are activated both by epithelial-derived cytokines such as IL-25, IL-33, and TSLP as well as leukotrienes found elevated in asthma, and yet ILC2 also produce amphiregulin, an important tissue repair mediator." (PMID 24876829, 2013). "This list included many genes with a purported role in regulation of the immune response in asthma: interleukins (IL2IL27 and IL33), chemokines (CXCL1CXCL17CCL5 and CCL27), mucins (MUC2MUC13 and MUCL1), TLR7 and NOS2, among others." (PMID 22713245, 2012). "Collectively, the data suggest that IL-33 is involved in lung inflammation and supports the concept of ST2 as a therapeutic target in asthma." (PMID 21871091, 2011). "In fact, it has been demonstrated that soluble ST2 acts as an antagonistic decoy receptor for IL-33 using a murine thymoma cell line, EL-4, which stably expresses ST2L, and a murine model of asthma." (PMID 20573196, 2010). "IL-33 was significantly elevated in females with asthma in comparison to males with asthma, and TSLP levels were not different in the plasma between any of the groups." (PMID 40821845, 2025). "H. polygyrus HES suppresses IL-33 responses in models of asthma and in helminth infection through down-regulation of ST2 transcription and through inducing IL-1β release, which in turn suppresses production of IL-33 and IL-25." (PMID 40302223, 2025). "Notably, allergen immunotherapy (AIT) can reduce viral exacerbation rates in patients with asthma by increasing the expression of type I/III IFNs and decreasing the expression of IL-33." (PMID 39962262, 2025). "The study conducted on people whose omentin expression in lungs was suppressed using nonsense mRNA showed that the synthesis of IL-25, IL-33, and TSLP was consequently decreased, directly linking omentin’s role in their production and, therefore, in the asthma development." (PMID 40149608, 2025).